IL6 (interleukin 6)
Diseases named in the same sentence as IL6 in open-access papers (continued):
Sharing a sentence is not in itself a finding about the gene and the disease.
Cachexia (continued). "Cytokines like TNFα, IFNγ, IL-1, and IL-6 are major promoters of the acute phase response, which increases muscle catabolism and resting energy expenditure, fostering cachexia." (PMID 40362192, 2025). "Proinflammatory cytokines such as IL-6, IL-1β, TNF-α, and IFN-γ are associated with muscle wasting in both clinical and preclinical cancer cachexia." (PMID 40469669, 2025). "IL-6 plays a paradoxical role; acute IL-6 surges from exercising muscle have anti-inflammatory and anabolic effects, whereas chronically elevated IL-6 (as in cachexia) becomes detrimental." (PMID 40869331, 2025). "Overall, these data show that tumor growth led to a significant increase in circulating levels of IL-6 and GDF15 before the onset of anorexia-cachexia, the latter being associated with plasma concentrations of these two cytokines above threshold values." (PMID 40124481, 2025). "Anti-inflammatory agents, like interleukin-6 (IL-6) inhibitors, have been explored to counteract the inflammatory drive of cachexia: IL-6 targets adipose tissue, skeletal muscle, and gut and liver tissue." (PMID 41010454, 2025). "In the mouse model of male C57BL/6J mice that were injected with Lewis Lung Carcinoma cells, inflammatory molecules such as TNFα and IL-6 showed a crucial role in triggering various secondary symptoms that affected nutrition and mental wellbeing in cachexia." (PMID 40362192, 2025). "Elevated levels of this pro-inflammatory cytokine, IL-6, are observed in many cancers, as well as in preclinical models, and IL-6 is a major pro-inflammatory factor involved in the systemic inflammatory condition that occurs in cachexia." (PMID 40869331, 2025). "They underscore its role in counteracting IL-6-mediated muscle fiber disruption in a cachexia model." (PMID 41226740, 2025). "Interventions targeting cachexia—such as anti-IL-6 therapies (e.g., tocilizumab) or structured nutritional support—represent promising directions to enhance ICI outcomes and warrant further investigation in randomized trials." (PMID 40940861, 2025). "Taken together, these results suggest that, according to previous findings, IL6 is the main driver of muscle atrophy in the experimental model of C26‐induced cachexia, whereas TNFα and myostatin only have marginal roles." (PMID 40448398, 2025). "In contrast, in cachexia, increased lipolysis is driven primarily by tumour-derived factors (e.g., IL-6, TNF-α, and PTHrP) and systemic inflammation, leading to a net loss of fat mass rather than fat accumulation (Joshi & Patel 2022)." (PMID 41373779, 2025). "Inflammatory cytokines such as IL-6 have also been shown to induce beige fat development in cachexia models." (PMID 40869331, 2025). "Although inflammatory markers such as IL-6 and CRP are mechanistically linked to cachexia and immune dysregulation, their inconsistent reporting across studies restricted meta-analytic synthesis." (PMID 40940861, 2025). "Pharmacological blockade of the JAK/STAT3 pathway has been shown to reduce muscle atrophy in C26‐driven cachexia, suggesting a significant role for this pathway in IL‐6/gp130‐mediated cachexia." (PMID 39764565, 2025). "Although the IL‐6 cytokine family has been widely investigated as a driver of cachexia with several cancers, how this signalling regulates muscle responses to feeding and fasting requires further study." (PMID 40931444, 2025). "We unexpectedly found that administration of BCAA led to a significant reduction in the plasma levels of IL6 in moderate cachexia." (PMID 40448398, 2025). "Sophocarpine and Matrine, which inhibit TNF-α and IL-6 production, reduced cachexia symptoms in animal models." (PMID 40519290, 2025). "Our study included a total of 49 patients with NSCLC and IL‐6‐elevated cachexia, treated at our institution from March 2019 to September 2023." (PMID 39523982, 2024). "Studies in rodents have elucidated a close association between the IL-6/IL-6R/STAT-3 cascade and muscle degradation during cachexia progression." (PMID 39703501, 2024).
Cachexia (continued). "Tocilizumab demonstrated significant benefits in survival and various clinical parameters, including body weight, albumin, CRP, mGPS and symptom burden in patients with NSCLC and concurrent IL‐6‐elevated cachexia." (PMID 39523982, 2024). "In this retrospective study, data were collected from patients with NSCLC and concurrent IL‐6‐elevated cachexia who received either tocilizumab plus antitumour therapy or antitumour therapy alone." (PMID 39523982, 2024). "The mRNA was isolated from mouse kidneys and was used to examine the expression levels of signaling proteins, inflammatory cytokines, and genes responsible for inducing cachexia (IL-1β, IL-6, TNF-α, TGF-β, GDF-15, and MYD88)." (PMID 39394174, 2024). "An important phenomenon accompanying cachexia is the inflammatory process, during which the secretion of proinflammatory cytokines is observed, including IL-1β, Il-6, IL8, TNF-α, and interferon-gamma (INF-γ)." (PMID 38610941, 2024). "The study included 49 patients diagnosed with NSCLC and IL‐6‐elevated cachexia, Eastern Cooperative Oncology Group performance status of 2–4." (PMID 39523982, 2024). "First, the induction of IL‐6, the main inflammatory driver of cachexia, was markedly blunted by AdipoRon consistently in the two animal models." (PMID 38572511, 2024). "In the adipose tissue during cachexia, numerous pro-inflammatory factors, such as TNFα, IL-1β, and IL-6, are stimulated." (PMID 39000187, 2024). "Our two knockout approaches—whole‐body Il‐6−/− and Li‐Stat3−/−—reveal the liver to be a novel target for IL‐6 signalling in cachexia." (PMID 38632714, 2024). "The measurement of their blood concentrations in our mouse cachexia model revealed increased IL6, TNFα, and HMGB1 concentrations in the CD group." (PMID 39125651, 2024). "Most commonly implicated pro-inflammatory cytokines in cachexia include TNF-α and interleukins IL-1, IL-6, and IL-8." (PMID 39684385, 2024). "The importance of cytokines in regulating hepatic metabolism during cachexia, with IL-6 being a primary mediator in the process, was also described." (PMID 39596015, 2024). "Elevated levels of pro-inflammatory cytokines, including tumor necrosis factor-alpha (TNF-α), interleukin-6 (IL-6), and interleukin-1 (IL-1), play a pivotal role in wasting syndrome." (PMID 38845818, 2024). "In contrast, another study has shown that 8 weeks of moderate treadmill exercise prevented IL6-induced cachexia in APCmin/+ mice and improved insulin sensitivity, muscle oxidative capacity, and muscle metabolism." (PMID 38791998, 2024). "IL-6 alone can induce most cachexia symptomatology, including muscle and fat wasting, the acute phase response, and anemia." (PMID 39684385, 2024). "Together, these results indicate that the IL-6Rα on AP neurons, especially that on Gfral+ neurons, is a critical mediator of IL-6 function in the development of cancer cachexia in the C26 model." (PMID 38824130, 2024). "Eicosapentaenoic acid, an α-3-ω fatty acid present in fish, was found to suppress IL-6 production in patients with cachexia, and its efficacy has been evaluated in randomized trials." (PMID 38510850, 2024). "PC(34:1), which abundance differed between patients with cachexia plus inflammation and non‐cachectic patients, was negatively correlated with skeletal muscle IL‐6 mRNA expression (rs = −0.38, P = 0.048)." (PMID 38725139, 2024). "The prototype of cachexia triggered by IL-6 showed that skeletal muscle atrophy was prevented by blocking JAK/STAT3 signaling." (PMID 39404384, 2024). "Together, these data indicate that RK prevents severe tissue atrophy in C26‐induced cachexia by reducing circulating IL‐6 concentrations and STAT3 signalling." (PMID 38302863, 2024). "Application of an anti-IL-6 antibody to an experimental tumor-bearing mouse model suppressed IL-6 secretion in the brain, which was accompanied by an attenuation of cachexia and hyperactivity in the area postrema network and prolonged the life of the mice." (PMID 39596487, 2024).
Cachexia (continued). "Underlying the pathogenesis of cachexia are many inflammatory cytokines such as tumor necrosis factor‐alpha (TNF‐α), interleukin‐1beta (IL‐1β), and interleukin‐6 (IL‐6), which cause malnutrition and loss of skeletal muscle mass." (PMID 39229565, 2024). "Consistent with prior research linking elevated serum IL-6 to cachexia, our findings also indicate that subjects with decreased albumin levels present with significantly elevated IL-6 concentrations." (PMID 38672257, 2024). "Based on this information, the authors suggested that the liver plays a significant role in the development of cachexia, and hepatic parenchymal cells can be activated by macrophage-mediated signaling to produce pro-inflammatory cytokines such as IL-6." (PMID 39596015, 2024). "It is reported that via directing the inflammatory response, the cachexia is significantly influenced by IL-6/JAK/STAT3 signaling." (PMID 39404384, 2024). "Since systemic inflammation is recognized as another feature of both experimental and clinical cachexia, the serum levels of interleukin 6 (IL-6) and tumour necrosis factor α (TNF-α) were measured." (PMID 39327432, 2024). "Cancer cachexia is associated with systemic inflammation, and some proinflammatory cytokines were found to induce muscle atrophy and lipolysis in cachexia, including IL-6 and TNF-α." (PMID 39519503, 2024). "As we observed, circulating levels of IL‐6, a major proinflammatory cytokine involved in several models of cachexia, were dramatically increased (∼60‐fold over control levels) in C26 mice and reduced by almost 55% by AdipoRon." (PMID 38572511, 2024). "In contrast, in the ME, IL-6 levels didn’t increase until after the onset of cachexia, while in the cortex IL-6 levels didn’t increase throughout the different stages." (PMID 38824130, 2024). "Along with body weight protection, IL‐6 signalling inhibition in cancer cachexia protected against muscle wasting by attenuating proteolytic systems." (PMID 38572511, 2024). "The tumor bearing animals also showed other features of cachexia, including increased IL-6 levels in the plasma and increased Fos expression in the AP network." (PMID 38824130, 2024). "Cytokines, particularly IL-6, play a crucial role in mediating the inflammatory response in cachexia." (PMID 39596015, 2024). "Several proinflammatory factors, such as transforming growth factor-β (TGF-β), interleukin-1β (IL-1β) and interleukin-6 (IL-6), are upregulated in adipose tissue during cachexia, which promotes ECM production." (PMID 38041133, 2023). "Increased production of cytokines, such as IFNγ, TNF-α, and IL-6, is a common feature of muscle wasting and cachexia." (PMID 37217930, 2023). "In a mouse model of cachexia, carnitine reduced the serum levels of IL-1 and IL-6, which are possible inducers of cancer cachexia, with slight effects on TNF-α." (PMID 37600065, 2023). "The crucial dependence of the CHX207 model on IL‐6 renders it suitable for studying the efficacy of STAT3 inhibitors (e.g. sorafenib), IL‐6‐, or IL‐6 receptor blocking antibodies (e.g. tocilizumab) to prevent fibrosarcoma‐induced cachexia." (PMID 36351437, 2023). "Taken together, with CHX207 fibrosarcoma, we present a novel cancer model for C57BL/6 mice that induces robust and reproducible IL‐6 dependent cachexia." (PMID 36351437, 2023). "It appears that when the body experiences cachexia due to chronic inflammation, the level of IL-6 is elevated, and IL-6 can suppress protein synthesis and activate several protein degradation pathways." (PMID 37730552, 2023). "Our data corroborate findings of prior studies suggesting that cachexia in male ApcMin/+ is Il6-dependent." (PMID 37960223, 2023). "IL‐6 likely plays a causal role in CAC development because cancer cell‐specific deletion of IL‐6 protected CHX207IL6‐KO mice from cachexia." (PMID 36351437, 2023).
Cachexia (continued). "Levels of proinflammatory cytokines (e.g., IL-6 and CRP) were also higher in the serum of cachectic patients than in the other two groups, thereby indicating that cachexia was associated with a highly inflammatory environment." (PMID 36973755, 2023). "Inflammatory cytokines such as IL-1, IL-6, TNF-α, and IFN-γ were commonly identified and associated with the development of cachexia." (PMID 36831513, 2023). "The extent of EC-derived IL-6, endothelial IL-6 signaling and its contribution to tissue wasting and cachexia remains elusive." (PMID 37222464, 2023). "Proinflammatory cytokines, particularly TNF-α, IL-6, and IL-1β, are considered to be important mediators of cachexia induction." (PMID 37446099, 2023). "The IL-6/JAK/STAT3 signaling has been found to have an important role in cachexia progression by regulating the inflammatory response." (PMID 37217930, 2023). "A literature review highlights the significant role of pro-inflammatory cytokines, such as TNF-α, IL-6, and IL-1, and certain chemokines, like CXCL8/IL-8, as procachectic agents produced by different TME cell types in CRC-associated cachexia." (PMID 37629689, 2023). "Several studies have demonstrated that chemotherapy-induced cachexia or CRF is associated with an increase in proinflammatory cytokines, such as TNF-α, IL-6, and IL-1β." (PMID 37699022, 2023). "We and others have shown that murine cancer cachexia models have elevated serum levels of IL-6 and LIF, which contribute to adipose wasting in this syndrome." (PMID 35785158, 2022). "Regarding cachexia, knockdown of Hotair in MBT-2 tumors ameliorated cisplatin-induced cachexia in terms of changes in body weight, serum IL-6 levels, muscle mass, and MuRF-1 expression." (PMID 36471329, 2022). "The main drivers of cachexia are cytokines such as interleukin-6 (IL-6), tumor necrosis factor-alpha (TNF-α), macrophage inhibitory cytokine 1 (MIC-1/GDF15) and transforming growth factor-beta (TGF-β)." (PMID 36078078, 2022). "In particular, circulating levels of IL-6 have been shown to positively correlate with cachexia in cancer patients, and importantly, IL-6 levels were found to negatively associate with their survival." (PMID 36408139, 2022). "Cachexia is a complex wasting syndrome characterized by systemic inflammatory responses, elevated pro-inflammatory cytokines (IL-1, IL-6, and TNF-α), and remarkable effects on the IGF-1/Akt and NF-κB pathways." (PMID 36139760, 2022). "Specifically, male ApcMin/+ mice are sensitive to inflammation (IL-6)-mediated cachexia, while female ApcMin/+ mice undergo cachexia progression IL-6-independently." (PMID 35626116, 2022). "The main cytokines driving cachexia are IL-6, TNF-α, TGF-β and MIC-1/GDF15 MIC-1/GDF15, a member of the TGF-β superfamily, is produced in large amounts by normal and cancer cells." (PMID 36078078, 2022). "The separate stimulation of TNF and IL-1β promoted the secretion of LIF and IL-6 in a cachexia study with tumor-bearing mice, resulting in a synergistic effect." (PMID 35740622, 2022). "Several pro-inflammatory cytokines such as TNF-α, IL-6, IL-1, and interferon-γ (IFNγ), either tumor-derived or host-derived, were reported to be upregulated in cachexia." (PMID 35646636, 2022). "Examples of anti-IL-6 monoclonal antibodies are tocilizumab, commonly used in autoimmune disease showing a better survival in cachexia mice, and clazakizumab, which demonstrated improved symptoms such as fatigue and weight loss." (PMID 36078078, 2022). "Human studies involving gastric, breast, and lung cancer patients (with or without cachexia) and healthy individuals showed a significant increase in IL-6 mRNA levels in cancer patients with cachexia compared to the other participant groups." (PMID 35328423, 2022). "IL-6, which is elevated in circulation in cachexia, induces adverse downstream effects via AMPK signalling in this context." (PMID 36479347, 2022).
Cachexia (continued). "Previous studies have identified several cachexia-related cytokines, including interleukin-6 (IL-6), tumor necrosis factor alpha (TNF-α), IL-1β, and the leukemia inhibitory factor (LIF)." (PMID 35740622, 2022). "Other pro-inflammatory cytokines, including IL-1 and IL-6 induced a strong reduction in transporters involved in bile formation and bile acid secretion, further aggravating the development of cachexia." (PMID 36119037, 2022). "Increased IL-6 levels and a positive correlation between serum IL-6 and free FAs was also reported in early and late-stage cachexia patients indicating a possible influence on WAT lipolysis." (PMID 35646636, 2022). "Blocking IL-6 and related signals have been shown to slow the progression of cachexia in several animal cancer models." (PMID 35159388, 2022). "Thena, an anaplastic thyroid cancer cell, induces cachexia in mice by expressing higher levels of IL-6, LIF, and TGF-β." (PMID 35740622, 2022). "Exogenous administration of IL-6 in ApcMin/+/IL-6−/− mice led to the development of the cachexia phenotype, a finding that delineates a possible central role of IL-6 in CCS pathogenesis." (PMID 35743911, 2022). "In current clinical studies, good progress has been made in improving cachexia with therapies that counteract key cachexia factors such as IL-6, IL-1β, and IL-1α." (PMID 35740622, 2022). "The absolute serum concentrations of IL-6 and LIF observed during RM9-associated cancer cachexia were 83 ± 20 ng/mL and 3.4 ± 0.8 ng/ml, respectively." (PMID 35785158, 2022). "In Apcmin/+ mice with severe cachexia, IL-6 secretion level increased significantly, which inhibited PPAR-α, resulting in hypoketosis and activation of the HPA axis, which ultimately led to increased glucocorticoid release and enhanced muscle proteolysis." (PMID 36139760, 2022). "IL-6 levels are high in PDAC models with weight loss, and IL-6 is functionally linked to cachexia in murine C26 colon adenocarcinoma and other models of cancer cachexia." (PMID 33851955, 2021). "Malignant cells signal via IL-6 to muscle and fat, muscle to fat via sIL6R, and fat to muscle via lipids and IL-6, all targetable mechanisms for treatment of cachexia." (PMID 33851955, 2021). "Collectively, these results are consistent with IL-6 as a KPC-derived mediator of cachexia and mortality." (PMID 33851955, 2021). "Because systemic inflammation represents a key pathophysiological mechanism in propagating development of cancer‐related cachexia, we performed an additional analysis to identify potential correlations between IL‐6 levels and the metabolomic parameters." (PMID 34636159, 2021). "Our data support this notion since the higher CRP levels of the ‘no cachexia’ group did not translate into increases in other inflammatory molecules known to be elevated in cachexia, such as IL-6, or the complement factors C3a, TCC, and C1q." (PMID 34830921, 2021). "Specifically, the inflammatory cytokines, IL-6, TNF-α and IL-1 have been implicated in CKD-associated cachexia." (PMID 34302016, 2021). "In our avatar models, mice exhibiting the highest levels of human IL-6 in plasma also had the highest severity of cachexia and mortality, implicating IL-6 arising from metastatic cells." (PMID 33851955, 2021). "The levels of TNF-α and IL-6 were significantly increased in the cachexia control group than in the normal control group (p < 0.01)." (PMID 34262449, 2021). "As such, cachexia is generally associated with increased levels of inflammatory molecules such as CRP, TNF-α, IL-6, and IL-8." (PMID 34830921, 2021). "In mice affected by severe cachexia (ApcMin/+ mice), IL-6 overexpression altered the expression of proteins regulating mitochondrial biogenesis and fusion in cultured myoblasts (C2C12 cells)." (PMID 33557173, 2021). "Malignant cells signal via IL-6 to muscle and fat, and muscle via sIL6R to fat, and fat via FAs and IL-6 to muscle, which are all targetable mechanisms for treatment of cachexia." (PMID 33851955, 2021).